KEAP1 (kelch like ECH associated protein 1)
Diseases named in the same sentence as KEAP1 in open-access papers (continued):
Sharing a sentence is not in itself a finding about the gene and the disease.
ischemic stroke (11 papers, 2016 to 2025). A stroke disorder caused by obstruction of blood flow to the brain, due to thrombotic (local blood clot formation) or embolic (due to a blood clot or other material traveling from another site) event. "Furthermore, soy isoflavones’ defense against ischemic stroke is linked to the stimulation of Nrf2 and the reduction of Keap1 activity." (PMID 40283984, 2025). "Given its pivotal role in cellular defense, the Keap1/Nrf2 pathway has emerged as a promising therapeutic target for neuroprotection in ischemic stroke." (PMID 40283984, 2025). "The up-regulation of miR-139-5p in the preconditioned EVs was found to inhibit the anti-apoptotic effects of the FoxO1/Keap1/Nrf2 pathway, thereby potentially alleviating the impact of ischemic stroke." (PMID 40873771, 2025). "The protective effects are likely mediated through the activation of the Nrf2/Keap1 signaling pathway, supporting the therapeutic potential of SI in ischemic stroke treatment." (PMID 40283984, 2025). "For ischemic stroke, GA exerts neuroprotection by suppressing HMGB1/TLR4/NF-κB signaling while activating the Kelch-like ECH-associated protein 1(KEAP1)/Nuclear factor erythroid 2-related factor 2(NRF2) antioxidant response." (PMID 41240391, 2025). "Despite its critical role in oxidative stress, Keap-1 has limited therapeutic significance in acute disease models such as ischemic stroke, largely due to its bio-refractory properties and long half-life (e.g., 12.7 h in HepG-2 cells)." (PMID 39682718, 2024). "Recently, a clinical study showed that NBP exerts a neuroprotective effect on ischemic stroke patients by regulating the Keap1/Nrf2 pathway." (PMID 36712684, 2022). "Nevertheless, the necessity and sufficiency of modification of Keap1 for the fumarate-mediated activation of Nrf2 in the setting of ischemic stroke remain unclear and warrant further investigations." (PMID 27614618, 2016). "In the process of exploring new drugs, up-regulation of autophagy has been found in numerous disease-model studies and activation of the p62/Keap1/Nrf2 pathway has been shown to play a role in alleviating systemic diseases and in ameliorating brain injury, such as ischemic stroke." (PMID 32038239, 2019). "The docking results indicated that CZK might interact with Keap1-Nrf2 Kelch domain effectively, demonstrating that CZK could treat ischemic stroke through Nrf2 pathway." (PMID 37055457, 2023).
osteosarcoma (11 papers, 2022 to 2025). A usually aggressive malignant bone-forming mesenchymal neoplasm, predominantly affecting adolescents and young adults. "Increased NRF2 expression in osteosarcoma has been associated with poor prognosis, but also mutations of both NRF2 and KEAP1 have been reported in osteosarcoma." (PMID 38534381, 2024). "A similar mechanism was observed in osteosarcoma, where KEAP1-259aa interacts with cytoplasmic Vimentin to regulate cell stemness, with Vimentin-induced multinucleation also affecting tumor cell stemness." (PMID 40307891, 2025). "Instead, KEAP1 activation, for instance by using exosomes, has been shown to induce cell death in osteosarcoma, increasing NRF2 ubiquitination and degradation." (PMID 38534381, 2024). "To do this, we first generated a cell line where Keap1 ectopically expressed as a fluorescently-tagged doxycycline (Dox)-inducible Keap1-mCherry protein was genomically integrated into human osteosarcoma U2OS cells." (PMID 35391936, 2022). "LAMTOR5-AS1 regulates the interaction between NRF2 and Kelch-like ECH-associated protein 1 (KEAP1) to inhibit NRF2 transcriptional activity under chemotherapeutic drugs treatment, which finally results in an increase in drug sensitivity in osteosarcoma." (PMID 35625948, 2022). "We assessed the interaction between PRL-295 and Keap1 ectopically expressed as a fluorescently tagged protein that was genomically integrated into human osteosarcoma U2OS cells, using a modified cellular thermal shift assay (CETSA) that we developed for this purpose." (PMID 35036882, 2022). "However, NRF2 can be ubiquitinated for degradation also by other E3 ligases such as TRIM22, which accelerates the ubiquitination and proteasomal degradation of NRF2 and increases autophagy but independently of KEAP1 activity, as seen in in vitro experiments on osteosarcoma." (PMID 38534381, 2024). "In osteosarcoma, TRIM22 has been observed to promote Keap1-independent degradation of Nrf2, thereby activating autophagy signaling pathways and ultimately impeding osteosarcoma progression." (PMID 39664581, 2024). "Taken together, these results reveal a crucial role of DDRGK1 in the KEAP1/NRF2/ROS pathway, which contributes to osteosarcoma development and chemoresistance." (PMID 36965071, 2023). "Similarly, the mRNA levels for pirin decreased by 50% upon knockout of Nrf2 in the human osteosarcoma cell line U2OS, in which the levels of Keap1 and Nrf2 are normal." (PMID 35204145, 2022). "TRIM22 inhibites osteosarcoma progression by promoting proteasomal degradation of NRF2 independent of KEAP1, thereby activating AMPK/mTOR/autophagy signaling that led to autophagic osteosarcoma cell death." (PMID 36261847, 2022).
psoriasis (11 papers, 2018 to 2025). An autoimmune condition characterized by red, well-delineated plaques with silvery scales that are usually on the extensor surfaces and scalp. "Dysregulation of the Nfr2/KEAP1 system has been associated with skin damage and psoriatic plaque formation in a psoriasis-mouse model." (PMID 37188635, 2023). "Dimethyl fumarate, initially used to treat psoriasis, was later discovered to be an inducer of the Nrf2/Keap1 pathway." (PMID 38519984, 2024). "Recently, Ogawa and Ishitsuka reviewed the role of Keap1-Nrf2 system in the pathophysiology of atopic dermatitis and psoriasis and the therapeutic approaches that utilize this system." (PMID 36421456, 2022). "Thus, ERN protects against psoriasis caused by IMQ through the antioxidant enzyme’s defense mechanism, which is aided by KEAP1-Nrf2." (PMID 40667480, 2025). "Increased Keap1 levels observed in psoriasis should mean stronger Nrf2 degradation." (PMID 30301214, 2018).
viral infection (11 papers, 2019 to 2024). "It has been reported that Nrf2 degradation caused by viral infection is regulated by Keap1-dependent or Keap1-independent ubiquitin–proteasome pathways." (PMID 35101046, 2022). "Taken together, the findings reported here provide insights into the molecular mechanism underlying viral infection induced Nrf2/Keap1 axis activation and reveal a novel paradigm for how cellular pathways can target virus components to facilitate anti-virus defense functions." (PMID 35139135, 2022). "Moreover, we found that virus infection destabilized the protein association between DJ-1 and KEAP1, which further supported the findings that virus infection promoted the ubiquitination of Nrf2." (PMID 31687081, 2019). "The rs2364723C/G is in an intron and may cause changes in mRNA splicing and alterations in protein isoforms, which could modify its interaction with KEAP1, resulting in a significant alteration in the NFR2-KEAP1 signaling pathways, causing genotypes with greater susceptibility to viral infection." (PMID 36613859, 2022). "Therefore, virus infection rendered DJ-1 loss capacity to protect Nrf2 degradation which facilitated the degradation of Nrf2 through the ubiquitin proteasome pathway mediated by KEAP1." (PMID 31687081, 2019). "During viral infection, Keap1 detects oxidative stress via the conjugation of redox-sensitive cysteine residues (Cys151, Cys273, Cys288), and Nrf2 is released from Keap1-mediated repression." (PMID 32722164, 2020). "Immunoprecipitation using the antibody against DJ-1 further confirmed that virus infection led to a reduced capacity of binding to KEAP1." (PMID 31687081, 2019). "In this study, our findings indicated that BoHV-1 infection promoted the proteasome degradation of Nrf2 in line with the increased expression of KEAP1 protein following the virus infection, suggesting that KEAP1 is potentially involved in the virus infection-induced degradation of Nrf2." (PMID 31687081, 2019). "We then examined the effects of virus infection had on the expression of KEAP1 in MDBK cells." (PMID 31687081, 2019). "The current studies highlight the significance of the Nrf2/Keap1 axis in the regulation of EIAV replication and broaden our understanding of antioxidant-stress induced by virus infection." (PMID 35139135, 2022). "In addition, we provide evidence that NFE2L2/KEAP1, FDFT1, and AHR are potentially druggable host targets with relevance for various viral infections." (PMID 38319076, 2024). "Little is known of the role of Keap1 in the regulation of viral infection except that Marburg virus (MARV) VP24 targets Keap1 to drive activation of Nrf2, which is likely to contribute to viral infection." (PMID 35139135, 2022). "In our study, Nrf2 was inhibited at 24 hpi, at this time, Keap1 was upregulated only in the virus infection group with an MOI of 1, but no significant change in higher MOI group." (PMID 35101046, 2022).
diabetic cardiomyopathy (10 papers, 2016 to 2026). Diabetic cardiomyopathy is a disorder of the heart muscle in people with diabetes. "While some evidence indicates that oxidative stress typically activates Nrf2 through Keap1 oxidation-induced nuclear translocation, our study revealed a paradoxical suppression of Nrf2 signaling in diabetic cardiomyopathy, with HG inhibiting Nrf2 protein expression in cardiomyocytes." (PMID 40529489, 2025). "Thus, sitagliptin is worthy of close attention not only as an anti-diabetic medication but also as a potent treatment for diabetic cardiomyopathy that targets the Nrf2/Keap1 signaling pathway." (PMID 38255895, 2024). "Thus, O-GlcNAcylation is crucial for explaining the impact of the Nrf2/Keap1 pathway on diabetic cardiomyopathy." (PMID 38255895, 2024). "For instance, phloretin may prevent diabetic cardiomyopathy via the dissociation of the Keap1/Nrf2 complex and inhibition of oxidative stress." (PMID 33042989, 2020). "Additionally, treating diabetic rats with phloretin attenuated diabetic cardiomyopathy by inhibiting the interaction between Nrf2 and Keap-1, independent of its hypoglycemic effect." (PMID 36986192, 2023).
fibrosarcoma (10 papers, 2015 to 2026). A malignant mesenchymal fibroblastic neoplasm affecting the soft tissue and bone. "The levels of Bcl2, BAX, musculoaponeurotic fibrosarcoma (Maf), Nrf2, Keap1, and PGC1α in the hippocampus were assessed using the western blot method." (PMID 37885999, 2023). "When Nrf2 exceeds the levels of Keap1, Nrf2 will escape the fixation by Keap1 and translocate into the nucleus, wherein it combines with the small musculoaponeurotic fibrosarcoma (sMaf) proteins to form Nrf2-sMaf heterodimer." (PMID 36439850, 2022). "KEAP1-independent regulation of NRF2 includes epidermal growth factor receptor (EGFR)/rat sarcoma virus (RAS)/rapidly accelerated fibrosarcoma (RAF)/extracellular signal-regulated kinase 1/2 (ERK) signaling which activates NRF2 and are also the driver genes of LUAD." (PMID 37305533, 2023). "Keap1: Kelch-like ECH-associated protein 1; Nrf2: Nuclear factor erythroid 2 p45 (NF-E2)-related factor; sMaf: Small musculoaponeurotic fibrosarcoma protein; ARE: Antioxidant response element; GSH: glutathione; SOD: superoxide dismutase; CAT: Catalase; GPx: Glutathione peroxidase." (PMID 33050575, 2020).
periodontitis (10 papers, 2013 to 2025). An acute or chronic inflammatory process that affects the tissues that surround and support the teeth. "The nuclear factor erythroid 2-related factor 2 (NFE2L2 or NRF2)/ Kelch-like ECH-Associated Protein 1 (KEAP1) (NRF2/KEAP1) signaling pathway plays a key role in periodontitis modulating redox balance and periodontium inflammation." (PMID 40736688, 2025). "Alterations of NRF2/KEAP1 signaling pathway have also been associated to osteoclastogenesis during periodontitis." (PMID 40736688, 2025). "The effects of the NRF2/KEAP1 pathway have also been proven in NRF2 knockdown mice model of periodontitis where NRF2 absence caused a more severe alveolar bone loss as well as an increased oxidative stress in periodontal tissue." (PMID 39456522, 2024). "The nuclear factor erythroid 2-related factor 2 (NFE2L2 or NRF2)/Kelch-like ECH-Associated Protein 1 (KEAP1) (NRF2/KEAP1) signaling pathway plays a key role in periodontitis by modulating redox balance and inflammation of the periodontium." (PMID 39456522, 2024). "N-Acetyl-l-cysteine-Derived Carbonized Polymer Dots may regulate redox homeostasis and promote bone formation in the periodontitis microenvironment by modulating the kelch-like ECH-associated protein l (Keap1)/nuclear factor erythroid 2-related factor 2 (Nrf2) pathway." (PMID 38800469, 2024). "Therefore, the experiments in vitro and in vivo confirmed that 4-OI ameliorated oxidative stress damage and alveolar bone destruction in experimental periodontitis through alkylating KEAP1’s cysteine residues to cause Nrf2-KEAP1 disassociation and consequent activation of Nrf2 pathway." (PMID 35637195, 2022). "An interesting review presents some important findings suggesting that the Nrf2/KEAP1 signaling pathway plays a significant role in the development of periodontitis-type inflammation." (PMID 41304943, 2025). "The importance of NRF2/KEAP1 signaling in periodontitis has been further validated in mice model of periodontitis." (PMID 40736688, 2025). "Several studies reported important effects of natural compounds in modulating NRF2/KEAP1 signaling in periodontitis models." (PMID 40736688, 2025). "It has been demonstrated that the NRF2/KEAP1 signaling pathway plays a key role in the onset and progression of several human diseases including periodontitis where this pathway modulates redox balance and inflammation of periodontium." (PMID 40736688, 2025). "In this review we explored the role of NRF2/KEAP1 signaling activation in in vitro and in vivo models of periodontitis to suggest potential treatments of periodontitis and avoid/delay the development of age-related neurodegenerative diseases." (PMID 40736688, 2025). "In fact, it has been demonstrated that NRF2/KEAP1 signaling is involved in the regulation of many cell processes that are altered in periodontitis." (PMID 39456522, 2024). "The results of RT‐qPCR showed that EGCG inhibited the expression of Keap1 and promoted the expression of Nrf2 and HO‐1, indicating that EGCG could play an antioxidative stress role in periodontitis through the Keap1/Nrf2/HO‐1 pathway." (PMID 40289388, 2025). "It has been demonstrated to regulate Keap1 protein stability by binding and ubiquitin–proteasome pathway, thereby alleviating inflammatory responses for the treatment of periodontitis, and this suggests that targeting ferroptosis-related genes for the treatment of periodontitis is feasible." (PMID 38802844, 2024). "In this review, we analyzed the current literature regarding the role of natural and synthetic compounds in modulating the NRF2/KEAP1 pathway in in vitro and in vivo models of periodontitis in order to evaluate new potential treatments of periodontitis that can improve the outcome of this disease." (PMID 39456522, 2024). "Overall, NRF2/KEAP1 signaling can be modulated by several natural compounds that could be used in combination with classical periodontitis treatments." (PMID 39456522, 2024).
periodontitis (continued). "The aim of this study was to investigate whether a Keap1-dependent oxidative stress detector-luciferase (OKD-LUC) mouse model would be useful for the visualization of oxidative stress induced by experimental periodontitis." (PMID 27854327, 2016). "Bomidin mitigated ferroptosis by activating the KEAP1/NRF2 pathway, ultimately alleviating the inflammatory response in periodontitis therapy." (PMID 40066457, 2025). "The multifaceted role of NRF2/KEAP1 signaling has been widely demonstrated in several cancerous and non-cancerous diseases, including periodontitis." (PMID 39456522, 2024). "Normally, the Keap1-Nrf2-ARE signalling pathway elicits an adaptive response for cell survival under oxidative stress but this did not appear to operate effectively in periodontitis patients." (PMID 23826097, 2013). "It is possible that in addition to potential over activation of Keap 1 or lack of Keap1 turnover, Nrf2 in neutrophils is post-translationally modified in periodontitis patients, which might interfere with its ability to undergo nuclear trafficking." (PMID 23826097, 2013). "Of note, turnover in Keap1 was evident in control subjects but not patients and this may indicate greater Keap 1 activity in periodontitis neutrophils which in turn may afford greater inhibition on Nrf2." (PMID 23826097, 2013). "Looking at the beneficial effects of NRF2/KEAP1 signaling activation reported in several studies, it is reasonable to think that increasing NRF2 expression in oral cavity could be an efficient therapeutic strategy for the prevention or treatment of patients with periodontitis." (PMID 39456522, 2024).
cardiac hypertrophy (9 papers, 2014 to 2025). "In conclusion, our results suggest that diosmetin protects cardiac hypertrophy under pressure overload through the p62/Keap1/Nrf2 signaling pathway, suggesting the potential of diosmetin as a novel therapy for pathological cardiac hypertrophy." (PMID 35242278, 2022). "In particular, diosmetin induced the accumulation of p62 and its interaction with Keap1, promoted the nuclear translocation of Nrf2, and increased the expression of antioxidant stress genes in the process of cardiac hypertrophy." (PMID 35242278, 2022). "Therefore, Wog has potential therapeutic value in myocardial hypertrophy and the Keap-1/Nrf-2 pathway might serve as a therapeutic target in the treatment of cardiac hypertrophy." (PMID 34290825, 2021). "Sheng Mai San ameliorates heat stress-induced cardiac hypertrophy, enhances the expression of antioxidant enzymes (GSH, SOD, and CAT), activates the Keap1-Nrf2 pathway in the heart, and restores oxidative stress balance." (PMID 40566495, 2025). "Interestingly, we did not notice pathological cardiac hypertrophy or diastolic dysfunction in association with the less robustly activated transcriptome in mNrf2-TG mice, suggesting that the expression of full-length Nrf2 is tightly under the control of its repressor, Keap1." (PMID 36140682, 2022).
endothelial dysfunction (9 papers, 2015 to 2025). In vascular diseases, endothelial dysfunction is a systemic pathological state of the endothelium (the inner lining of blood vessels) and can be broadly defined as an imbalance between vasodilating and vasoconstricting substances produced by (or acting on) the endothelium. "Recently, our group found that the miR‐200a/Keap1/NRF2 axis played an essential role in protecting against diabetes‐induced endothelial dysfunction." (PMID 32628815, 2020). "Dietary resveratrol, an antioxidant, was found regulating placental antioxidant genes expression by the Keap1-Nrf2-HO-1 pathway in placenta and features of placental and endothelial dysfunction characteristic of preeclampsia were improved." (PMID 30216983, 2018). "Associated with the upregulation of angiogenesis‐related proteins, including VEGFR, VEGF, Erk, Nrf2, Keap1, HO‐1 and HIF‐1α, HBO treatment rescues limb ischaemia‐induced endothelial dysfunction." (PMID 39720917, 2024). "Further, supplementation of miR‐200a inhibited aortic Keap1 expression, activated NRF2 signalling and attenuated hyperglycaemia‐induced oxidative stress, inflammation and endothelial dysfunction in the wild‐type, but not Nfe2l2 knockout, mice." (PMID 32628815, 2020). "Overall, these findings reveal a more critical role for Siah2, rather than Keap1, as a molecular regulator of hypoglycemia-induced Nrf2 degradation and BBB endothelial dysfunction." (PMID 25807533, 2015).